AR (androgen receptor)
Diseases named in the same sentence as AR in open-access papers (continued):
Sharing a sentence is not in itself a finding about the gene and the disease.
cancer (continued). "It has been reported in a non-cancer model that AR physically interacts with NRF2, and this interaction was increased by DHT." (PMID 36213236, 2022). "KDM3A is upregulated in several cancers and coordinates with multiple oncogenic transcription factors (e.g., c-Myc, androgen receptor, estrogen receptor, β-catenin, hypoxia-inducible factor-1α, etc.)to promote cancer progression and therapeutic resistance." (PMID 35625569, 2022). "As a cofactor of AR, HP1β upregulates the transcription of AR target genes and contributes to cancer proliferation." (PMID 35159030, 2022). "TLEs are also involved in estrogen receptor (ER) and androgen receptor (AR) signaling pathways, and both pathways provide important survival signaling for cancer cells expressing these receptors." (PMID 36438567, 2022). "In support of the more recent reports, our survey of publicly available AR data show that, relative to other cancers, AR protein and mRNA expression in HCC is relatively high." (PMID 36430245, 2022). "The M and MSL subtypes are enriched for metaplastic carcinomas (with low-proliferation seen in the MSL subtype) whereas LAR accounts for TNBCs with androgen receptor (AR) expression." (PMID 35444182, 2022). "For apocrine differentiated carcinomas, treatments targeting the androgen receptor (AR) have recently attracted attention due to their characteristic AR expression." (PMID 36553136, 2022). "In cancer biological research, AR has been reported to be expressed in many cell types, and androgen/AR signaling has been found to promote tumorigenesis and metastasis in several cancer types, including OCVA." (PMID 34299364, 2021). "This type of cancer is driven by the androgen receptor (AR) signaling pathway, and therefore AR-targeting drugs in androgen-deprivation therapy are currently the primary therapeutic option for PCa." (PMID 34681904, 2021). "Since the growth and function of the prostate gland as well as cancer cells are dependent on the action of steroid hormones androgens, targeting androgen production or signalling of AR is used for treatment of recurrent and metastatic PCa." (PMID 34940756, 2021). "We acknowledge that the functions of androgen/AR in embryonic and somatic stem cells have been shown to be tissue type-dependent, and the role of AR in cancer stem cells have been controversial which again demonstrates the significance of our studies." (PMID 34094902, 2021). "Androgen receptor (AR) is a steroid hormone receptor overexpressed in several types of cancer and is inversely correlated with survival rate." (PMID 34485285, 2021). "Of these, VPC-220010 demonstrated superior inhibitor activity in AR transcription and AR-dependent growth of cancer cells compared to EPI-001." (PMID 34298700, 2021). "AR targeted therapy used in metastatic PCa can lead to epithelial plasticity that enables adaptation of cancer cells, with the emergence of NE and EMT markers that contribute to treatment failure." (PMID 34204608, 2021). "The transcription factor FOXA1 has been proven to regulate transcriptional programs in both normal prostate tissue and cancer tissues by directly interacting with AR." (PMID 34445492, 2021). "The AR signaling axis, which is a PC characteristic, plays a key role in cancer progression, with ADT being the mainstay of therapy." (PMID 34761497, 2021). "These aberrant forms of AR have been detailed in our cancer model and are specific for AR; however, their functional relevance has not been determined." (PMID 34439133, 2021). "It is well established that AR signaling drives PCa progression by upregulating the expression of cell survival and cancer-related genes in AR-positive PCa cells." (PMID 34685704, 2021). "Collectively, these data point to KLF5 having divergent effects on cancer phenotypes, which are likely influenced by AR levels, epithelial cell identity, KLF5 levels, KLF5 acetylation, and hormonal milieu, among other factors." (PMID 34737261, 2021).
cancer (continued). "AR and ER are transcription factors that regulate the expression of genes involved in cancer development and progression, but also genes that are essential for the normal functioning of the prostate and breast glands." (PMID 34209750, 2021). "In order to deal with a complete diminishment of direct AR activation, cancer cells have started learning to “survive” in the environment poverty of AR signaling." (PMID 35008817, 2021). "Knocking down SARCC decreases the expression of miR-143-3p and stimulates multiple oncogenes by enhancing androgen receptor expression, which leads to greater cancer cell proliferation, migration, and invasion." (PMID 34958632, 2021). "The AR antagonist, bicalutamide, attenuated the AR/miR-125b axis, induced pro-apoptosis genes, and lead to cancer cell apoptosis and growth inhibition." (PMID 33947843, 2021). "These include either the specific upregulation of CYP17A1 or the overexpression of androgen receptors (AR) by cancer cells." (PMID 34579444, 2021). "Inhibition of this interaction would prevent AR chromatin binding preventing it from oncogenic signals that enable the progression of cancer." (PMID 33993099, 2021). "On the other hand, despite the very low serum androgen levels, most castration-resistant cancers remain dependent on the androgen receptor signaling pathway." (PMID 33466491, 2021). "The next two sections aim at answering these questions: (i) is AR targeting an effective means to enhance anti-cancer immunotherapy?" (PMID 34831054, 2021). "The onset, development and progression of PCa depends on androgenic hormone activation of the receptor and from the early work of Huggins and Hodges the AR is recognized as a crucial drug target in the fight against this cancer." (PMID 33572755, 2021). "Previous studies have shown some of the HDACis such as SAHA and dacinostat efficiently suppressed AR regulated transcriptional activities in PCa tissues, and more so effectively in AR-positive cancers." (PMID 33800156, 2021). "Here, we review the molecular mechanisms that enable cancer cells to switch from an AR-positive to AR-negative disease and efforts to prevent or revert this process and thereby sustain or restore AR dependence." (PMID 33420371, 2021). "ER and AR are transcription factors whose aberrant function drives oncogenic transcriptional programs to promote cancer growth and progression." (PMID 34209750, 2021). "PC is a hormone-dependent disease, in which the activation of the androgen receptor (AR) strongly promotes cancer progression." (PMID 34638444, 2021). "Here, we review the molecular mechanisms that enable cancer cells to switch from an AR-positive to an AR-negative disease and efforts to prevent/revert this process and thereby maintain/restore AR-dependence." (PMID 33420371, 2021). "These AR-independent pathways can promote cancer cell survival and growth and appear to be a significant androgen-independent driver of AR-regulated gene expression." (PMID 34681618, 2021). "One molecular consequence of AR loss in advanced UBC is that AR suppresses transcription of CD44, which encodes a cancer stem cell marker that mediates UBC aggression." (PMID 34768683, 2021). "In terms of appropriate models, it is challenging to investigate interactions between interleukins and AR in cancer precursor lesions, such as high grade prostate epithelial neoplasia." (PMID 34204596, 2021). "Specifically, they identified two AR interaction clusters, containing 21 and 30 proteins respectively, that showed an unfavorable outcome of recurrent cancers based on PSA, Gleason score, and combined PSA/Gleason score." (PMID 34638309, 2021).
cancer (continued). "Several preclinical studies have shown that xenografts of AR-dependent LNCaP cells in castrated mice significantly increased the number of cancer cells positive for NE markers." (PMID 34204608, 2021). "Aberrant AR signaling has been considered a pivotal player in transforming clinically localized hormones into aggressive-resistant cancers." (PMID 33499881, 2021). "To control for their ability to target TRF2-overexpressing cancers, we analyzed the potential anti-tumorigenic effects of AR and AD on both standard BJ-HELTRas cells and TRF2-overexpressing BJ-HELTRas cells." (PMID 34203903, 2021). "It is notable that FABP7 and AR were selected as differentially expressed genes which were upregulated in cancer cells in metastatic lymph nodes." (PMID 33816302, 2021). "Our preclinical studies suggest that AR is a potential therapeutic target for this deadly cancer type, especially in female patients." (PMID 33947843, 2021). "LINC00278, SLNCR1, SARCC and HOTAIR are other lncRNAs whose effects on AR have been investigated in different cancer types." (PMID 34831421, 2021). "In glioma, the circ-ASPH/miR-599/AR/SOCS2-AS1 axis has been identified as a molecular mechanism for cancer progression." (PMID 34831421, 2021). "Preclinical evidence also reveals that AR inhibition can inhibit cancer cell growth and improve outcomes in patients with BC." (PMID 33494738, 2021). "The E3, MDM2, promotes cancer stemness with an AR-negative signature in PCSCs by selectively degrading AR proteins." (PMID 34948357, 2021). "ADT with AA or enzalutamide will at first suppress the androgen receptor signaling axis and thus cancer cell growth." (PMID 34298770, 2021). "The effect of AR or miR-125b on the poor prognosis of female patients suggested that the male hormone, when abnormally disturbed in female cancer cells, has a more deleterious impact on the clinical outcome." (PMID 33947843, 2021). "On the contrary, post-menopausal women’s breasts, characterized by higher expression of ER, PR and AR in the epithelial component, tend to develop ER+/PR+/AR+ cancers." (PMID 34066838, 2021). "Dysregulation of the androgen/AR axis can lead to cancer cell proliferation, escaping from apoptosis, and metastasis." (PMID 33535458, 2021). "FOXA1 has been found to regulate estrogen receptor binding as well as AR and GR binding in both normal and cancer cells." (PMID 34227937, 2021). "While the mechanisms by which AR specifically binds to the CRY1 locus and induces CRY1 expression remain undefined, these findings identify a target of AR-regulation that promotes cancer phenotypes." (PMID 33452241, 2021). "A recent meta-analysis evaluated the effects of statin use on treatment outcomes (i.e., overall survival and cancer-specific survival) among patients with advanced PCa treated with ADT or AR signaling inhibitors." (PMID 35582011, 2021). "This is a multifaced type of cancer, in which often cells still depend on AR for migrating or growing in presence of very low levels of circulating androgens." (PMID 35011576, 2021). "VDR coexpression with AR and ER in cancer-surrounding breast tissue contributed to more favorable outcomes." (PMID 34638264, 2021). "Although APP is positively associated with androgen receptor, a recent study reported a marginal association between APP and AR expression in luminal A cancer." (PMID 34066808, 2021). "A recent meta-analysis evaluated the effects of statins use on treatment outcomes (i.e., overall survival and cancer‐specific survival) among patients with advanced PCa treated with ADT or AR signaling inhibitors." (PMID 34386430, 2021). "Androgen receptor (AR), a target gene of hsa-let-7i-5p and has-miR-320a, was enriched in pathways in cancer." (PMID 34122072, 2021). "In ERG‐positive cancers, the percentage of patients with strong AR expression was drastically increased despite low JUP levels." (PMID 33533127, 2021).
cancer (continued). "Targeting the DDR alongside the AR has recapitulated the potential of synthetic lethality in cancer treatment." (PMID 33525365, 2021). "Despite such advances in a precision medicine approach for other cancers, PCa treatment options have lagged behind this transition to broader biomarker targeted approaches beyond androgen receptor (AR) pathway modulating therapeutics." (PMID 33947030, 2021). "It is noteworthy that KEGG pathway analysis of JUN, AR revealed that these gene are key members of the pathways in which small disruption will unfortunately leads to cancer." (PMID 34588861, 2021). "Early application of PARPi is worth taking a look at, because PARP overexpression seems to not only promote DDR, but also enhance AR transcriptional function in advanced mCRPC and thus prevent cancer cell apoptosis." (PMID 34298770, 2021). "Sustained activation of AR signaling in cancer cells even under androgen depletion therapy is thought to be the primary mechanism of CRPC." (PMID 35008817, 2021). "Our lead P-box inhibitor VPC-17005 suppressed androgen signaling, demonstrated AR specificity through mutagenesis studies, and inhibited the growth of AR-positive cancer cell lines." (PMID 33801338, 2021). "Specifically, we explore how the intricate cellular signalling pathways that keep mRNA translation in check are perturbed by aberrant ER and AR signalling, which can lead to enhanced cancer cell growth." (PMID 34209750, 2021). "For example, TRIM24 controls AR-driven transcriptional regulation in PC but also general cancer mechanisms including EMT." (PMID 34208621, 2021). "Findings in AI-treated ER+ cancers are complicated by the induced increase in circulating and intratumoral androgens, and some metastatic AI-resistant ER+ cancers with mESR1 exhibited increased AR expression/and target genes." (PMID 34359625, 2021). "The AR also impacts cancer progression by binding to genomic androgen response elements, which affect the transcription of AR target genes." (PMID 34209597, 2021). "AR is known to possess sixteen phosphorylation sites, although some are occupied only in cancer cell lines or after medication (e.g., antiandrogens)." (PMID 34638264, 2021). "AR reduction in epithelial cells also accelerates these cells to differentiate into cancer stem-like cells and neuroendocrine cells, which are AR-negative PCa cells and inherently resistant to ADT treatments." (PMID 34692685, 2021). "Since the revelations that both AR and ERα can be successfully targeted to treat cancer, the idea of pharmacologically targeting nuclear receptors for cancer treatment has been a major research focus." (PMID 34825698, 2021). "Nonetheless, the fundamental mechanism responsible for stimulating the growth of cancer cells in PC is the activity of AR." (PMID 34638876, 2021). "Considering all cancers, the fraction of patients with strong AR expression was ~ 15% in the subset of patients with low JUP expression, but ~ 45% in the subset of patients with high JUP expression." (PMID 33533127, 2021). "A significant association was found between >/=20% AR positive epithelium cells in cytoplasm, Ki67 and VEGF in cancer stroma." (PMID 33920263, 2021). "We found that androgen-regulated genes with AR- and OCT4-bindings were associated with signal transductions in cells, particularly pluripotency of stem cells and pathways in cancer." (PMID 34145268, 2021). "Pre-clinical models consistently indicate that early interventions, including castration and genetic knockout of AR, inhibit cancer onset and burden, whereas later stage interventions exhibit significantly less anti-cancer activity." (PMID 33574348, 2021). "Yet, the mapped genes were highly relevant to PCa etiology and included known cancer drivers LDLRAD4, GMNN, COL1A1, CD38, PTPRN2, GTSE1 and CAMK2N1 in the risk signature and KLK2, AR, KLK3, SPDEF in the relapse signature." (PMID 33845808, 2021).
cancer (continued). "Of clinical relevance are the associations between co-expressed AR/β-catenin and Gleason grade 4–5 tumors and higher PSA levels, and the enrichment of AR and Wnt signaling in patients with early stage cancer." (PMID 33672595, 2021). "Since AR levels rapidly fall in response to elevated testosterone, the testosterone flare has the potential to prime cancer cells for a strong response when testosterone levels then decline to castrate levels." (PMID 34575033, 2021). "Despite the advancement of disease to castration-resistant prostate cancer (CRPC), the cancer cells remain dependent on the AR signaling pathway for growth." (PMID 34948018, 2021). "In this regard, a comprehensive proteomic profile revealed at least 12 miRNAs able to regulate AR expression, playing a role in cancer progression." (PMID 33499881, 2021). "In ERα+ cancers AR is positively related to lower grade, reduced node involvement, longer disease-free survival and these relations are AR level-dependent." (PMID 34638264, 2021). "Further understanding and application of ASC-J9® in the treatment of PCa, including AR-dependent and AR-independent anti-cancer effects, can help in the development of novel therapies to better suppress PCa progression." (PMID 33390173, 2021). "The androgen receptor (AR) signaling axis is critical during all stages of PC genesis and plays a crucial role in cancer occurrence and progression." (PMID 34761497, 2021). "Previous studies have reported that AR plays crucial roles in the progression of malignant neoplasms such as prostate, bladder, lung and breast cancers." (PMID 34907204, 2021). "In hormone-sensitive PC, the cancer cells rely on androgen binding to the AR to induce tumourigenesis." (PMID 34381019, 2021). "Normal prostate and carcinoma cells typically express the androgen receptor (AR) and are dependent on its signaling." (PMID 33537086, 2021). "We begin with a review of the various processes known to be mediated by AR signaling, as recent studies have shed light on the role of AR with other pathways known to be abrogated in cancer." (PMID 33062889, 2020). "Nonetheless, in oncogenesis and established cancer, these mechanisms either become altered or subverted to allow tumorigenic AR activity." (PMID 33076388, 2020). "One of the major functions of AR in cancer progression is to facilitate cell migration and metastasis." (PMID 32781788, 2020). "Several studies demonstrated that impairment of SREBP-1/FASN/lipogenesis and the AR axis leads to apoptosis in cancer cells." (PMID 32276528, 2020). "The inhibitory effect on the malignancy of PCa cells was further improved by blocking PSMA and extinguishing the expression of AR, leading to complete AR silencing and about a 50% reduction in the growth and malignancy of cancer cells." (PMID 32784981, 2020). "The dissection of biological function domains of PMEPA1 isoforms associated with AR and TGF-beta signaling potentially lead to novel anti-cancer therapeutics development." (PMID 32842649, 2020). "In this review, we will characterize metabolic phenotypes of PCa in relation to AR signaling and review the current knowledge of metabolism-based imaging tools and therapeutic interventions to target cancer metabolism." (PMID 33163409, 2020). "Significance of AR expression was correlated with prognostic biomarkers including cancer stem cell markers (CD44, CD24, and ALDH1), basal markers (CK5, CK14, and nestin), proliferation marker (ki-67), apoptotic marker (Bcl-2), and COX-2." (PMID 32850312, 2020). "Until now, some agents targeting multiple metabolic pathways or AR pathways have been used into pre-clinical studies to improve “cancer kill” and reduce the toxic side effect." (PMID 32431616, 2020). "In this review, we will discuss how androgens and the AR influence immune cells and cancer incidence and progression." (PMID 32714315, 2020).